ZAR1 (zygote arrest 1)
Description:
mRNA-binding protein that mediates formation of MARDO (mitochondria-associated ribonucleoprotein domain), a membraneless compartment that stores maternal mRNAs in oocytes. MARDO assembly around mitochondria is directed by an increase in mitochondrial membrane potential during oocyte growth. Promotes formation of MARDO phase-separated membraneless compartment by undergoing liquid-liquid phase separation upon binding to maternal mRNAs. Binds to the 3'-UTR of maternal mRNAs. Maternal mRNAs stored in the MARDO are translationally repressed. Essential for female fertility and oocyte-to-embryo transition by coordinating maternal mRNA storage, translation and degradation.
Synonyms: Z3CXXC6
Tractability: PROTAC: UniProt records ubiquitination sites on it; ubiquitination databases record sites on it.
Gene: Protein-coding gene on chromosome 4 (48,490,252 to 48,494,389, forward strand). Ensembl gene ENSG00000182223.
Subcellular location: Cytoplasm, Cytoplasmic ribonucleoprotein granule; Cytoplasm
Gene Ontology:
Molecular function: protein binding; molecular condensate scaffold activity; mRNA 3'-UTR binding; RNA sequestering activity; mRNA binding
Biological process: membraneless organelle assembly; mRNA stabilization; negative regulation of translation; oocyte maturation
Cellular component: cytoplasm; intracellular membraneless organelle; ribonucleoprotein granule; cytoplasmic ribonucleoprotein granule
Genetic constraint (gnomAD): Loss-of-function variants: 39 observed, 30.89 expected, observed/expected ratio (o/e) 1.26, 90% interval 0.98 to 1.65. The synonymous counts are far from expectation, so gnomAD's model fits this gene poorly and the ratio says little. Missense variants: 651 observed, 452.92 expected, observed/expected ratio (o/e) 1.44, 90% interval 1.35 to 1.53. Synonymous variants: 336 observed, 212.34 expected, observed/expected ratio (o/e) 1.58, 90% interval 1.45 to 1.73.
Homologues: Orthologues: chimpanzee ZAR1 (98% identical), macaque ZAR1 (92% identical), pig ZAR1 (66% identical), dog ZAR1 (51% identical), rat Zar1 (50% identical), mouse Zar1 (48% identical), tropical clawed frog zar1 (45% identical), zebrafish zar1 (40% identical). Paralogues in human: ZAR1L (31% identical).
Diseases named in the same sentence as ZAR1 in open-access papers:
ZAR1 is named in the same sentence as 25 diseases in open-access papers, as found by Europe PMC text mining. Sharing a sentence is not in itself a finding about the gene and the disease. The quoted sentences say what the papers report.
Infertility (4 papers, 2023 to 2024). "The underlying molecular mechanism and the role of Zar1l in oocyte meiotic maturation have been well characterized to only strengthen the Zar1 infertile phenotype in another study." (PMID 38786026, 2024). "Ultimately, embryos derived from ZAR1 null oocytes are blocked at 1‐cell stage embryos, resulting in the infertility of ZAR1 maternal KO female mice." (PMID 37547174, 2023). "Similarly, in mice, the disruption of zar1 results in infertility due to a delay in germinal vesicle breakdown and first polar body emission." (PMID 37566603, 2023). "However, despite extensive research in various animal models, no deleterious variant of ZAR1 has been reported thus far in women with infertility." (PMID 36732629, 2023).
neuroblastoma (4 papers, 2017 to 2025). Neuroblastoma (NB) is the most common solid, extracranial childhood tumor. "In parallel with our findings, it has been reported that the hypermethylation of the ZAR1 gene was also accompanied by its upregulation in neuroblastoma." (PMID 40949798, 2025). "In hypermethylated neuroblastoma, however, expression of ZAR1 was detected and indicated that ZAR1 knockdown promotes differentiation in neuroblastoma cells." (PMID 31801617, 2019). "The gene ZAR1 from UPUP-only group has been reported to be hypermethylated and upregulated in neuroblastoma, while CPT1B was upregulated in PCa and breast cancer, in which the gene promotes chemo-resistance." (PMID 31914996, 2020). "Expression of ZAR1 was absent in hypermethylated glioma cell lines, but ZAR1 was detected in hypermethylated neuroblastoma." (PMID 28588743, 2017).
breast carcinoma (3 papers, 2007 to 2020). "The focal CNAs contained several cancer relevant genes, such as the known breast cancer genes EGF, CDKN2A and BAG1 and some were less established including ZAR1 and BMS1." (PMID 33168853, 2020).
malignant melanoma (3 papers, 2013 to 2019). "In melanoma, the methylation of exon 1 was reported, but ZAR1 was said to be overexpressed in some hypermethylated melanoma cell lines." (PMID 31801617, 2019). "ZAR1 is methylated in various cell lines, in all germ cell lines (n = 14), in half of the malignant melanoma (n = 4) and kidney cancer cell lines (n = 4), in all mamma (n = 3), and 90% of brain cancer cell lines (glioblastoma; n = 8)." (PMID 31801617, 2019). "In malignant melanoma, ZAR1 was intra-genically methylated (exon 1) and ZAR1 was overexpressed in some hypermethylated melanoma cell lines." (PMID 28588743, 2017). "They examined differentially methylated regions in the exon of zygote arrest 1 (ZAR1) that had never been linked to aberrant methylation in melanomas and brain tumors." (PMID 23678400, 2013).
hepatocellular carcinoma (2 papers, 2013 to 2017). A malignant tumor that arises from hepatocytes. "In hepatitits C virus, positive hepatocellular carcinoma ZAR1 hypermethylation of exon 1 was found." (PMID 28588743, 2017).
lung carcinoma (2 papers, 2017 to 2019). "Lung cancer remains the leading cause of cancer death by far, and we published that ZAR1 is a novel tumour suppressor in lung cancer." (PMID 31801617, 2019). "ZAR1 came to our attention due to a 450k methylation array in which we identified it as one of the most strongly methylated target genes in a lung cancer cell line." (PMID 31801617, 2019). "We are also the first to report that ZAR1 methylation and expression reduction are of clinical importance as a prognostic marker for lung cancer and kidney cancer." (PMID 31801617, 2019). "We are the first to report that ZAR1 is epigenetically inactivated not only in lung cancer but also across cancer types, and ZAR1 methylation occurs across its complete CpG island." (PMID 31801617, 2019). "In lung cancer cell lines, ZAR1 was significantly methylated in 75% of SCLC and 83% of NSCLC vs. normal tissue (p < 0.005/0.05)." (PMID 28588743, 2017). "We found that ZAR1 is expressed in normal lung, but its expression is lost in lung cancer cell lines." (PMID 28588743, 2017). "Our analyses of ZAR1 therefore define ZAR1 as a heavily methylated CpG island carrying gene, which is epigenetically inactivated in lung cancer." (PMID 28588743, 2017). "Colony formation assays were performed in A549, A427 and HTB171 lung cancer cells that are epigenetically inactivated for ZAR1." (PMID 28588743, 2017). "Demethylation treatment of various lung cancer cell lines reversed ZAR1 promoter hypermethylation and subsequently re-established ZAR1 expression." (PMID 28588743, 2017). "ZAR1 expression was undetectable in various lung cancer cell lines as A427, A549 and H322, HTB171 and also in HeLa cervix cancer cells." (PMID 28588743, 2017). "All lung cancer cell lines exhibited decreased ZAR1 levels (<5%) vs. normal lung, except for H358, which was 15%." (PMID 28588743, 2017). "We chose lung cancer cell lines with ZAR1 promoter hypermethylation for demethylation treatment in cell culture." (PMID 28588743, 2017). "In our study, we aimed to establish ZAR1, which we found as a candidate from a 450 K methylation array, as an epigenetically inactivated tumour suppressor in human lung cancer." (PMID 28588743, 2017). "Our study shows that ZAR1 is expressed in normal lung but inactivated by promoter methylation in lung cancer." (PMID 28588743, 2017). "It will be interesting to study the ZAR1 hypermethylation together with other known lung cancer tumour suppressors, e.g. RASSF1A and RASSF10." (PMID 28588743, 2017). "Based on our findings that ZAR1 is epigenetically inactivated in lung cancer cell lines and primary lung cancer tumours, we aimed to test its tumour suppressive properties." (PMID 28588743, 2017). "Together with the observed epigenetic inactivation of ZAR1 in lung cancer and other cancer cell lines, we propose ZAR1 to be an epigenetically inactivated tumour suppressor in lung cancer." (PMID 28588743, 2017). "In our epigenetic work on ZAR1, we investigated the connection of promoter hypermethylation and repression of expression in the context of lung cancer." (PMID 28588743, 2017). "In contrast, we found promoter hypermethylation of ZAR1 not only in lung cancer cell lines but also in primary lung cancer of the SCLC and NSCLC subtype." (PMID 28588743, 2017). "We earlier reported that ZAR1 is epigenetically regulated in lung cancer." (PMID 31801617, 2019). "We next questioned if the observed growth inhibition of lung cancer cells by reexpressed ZAR1 could be due to increased apoptosis or arrest of cell cycle progression." (PMID 28588743, 2017). "In our study, we found that ZAR1 is epigenetically inactivated in lung cancer." (PMID 28588743, 2017). "This growth reduction by ZAR1 was significant for all three lung cancer cell lines when quantified." (PMID 28588743, 2017). "We therefore suggest that in the future, ZAR1 could serve as a hypermethylated biomarker for lung cancer detection and possibly could help differentiate between SCLC and NSCLC." (PMID 28588743, 2017).
lung carcinoma (continued). "We further found evidence that ZAR1 acts as a tumour suppressor and therefore suggest it could serve as a biomarker in lung cancer cells." (PMID 28588743, 2017). "In larger sample sets of SCLC and NSCLC as well as lung cancer metastases, one could narrow the time point when ZAR1 becomes hypermethylated and inactivated during lung carcinogenesis." (PMID 28588743, 2017). "In summary, we could show the epigenetic inactivation of ZAR1 in lung cancer for the first time." (PMID 28588743, 2017). "We propose that ZAR1 could serve as an epigenetically inactivated biomarker in lung cancer." (PMID 28588743, 2017). "Furthermore, we could restore ZAR1 expression in lung cancer cell lines pharmacologically by inhibition of DNA methyltransferases." (PMID 28588743, 2017). "In addition, we could show the growth inhibitory potential of ZAR1 in lung cancer cell lines and cancer cell lines." (PMID 28588743, 2017). "In lung cancer cell lines (A247, A549, HTB171, H322, H1299) and HEK cells, the ZAR1 promoter was highly methylated as analysed by COBRA, in HeLa and H358 lung cancer cells partially methylated and in HCC-15 lung cancer cells unmethylated." (PMID 28588743, 2017). "We chose different cancer cells as A549 (lung cancer), HeLa (cervix carcinoma) and HCT116 (colon carcinoma) for reexpression of ZAR1." (PMID 28588743, 2017). "ZAR1 is hypermethylated in primary lung cancer samples (22% small cell lung carcinoma (SCLC) and 76% non-small cell lung carcinoma (NSCLC), p < 0.001) vs. normal control lung tissue (11%)." (PMID 28588743, 2017). "ZAR1 (zygote arrest 1) was amongst the most strongly deregulated genes, and up to date, no study investigated the epigenetic inactivation of the ZAR1 promoter and its consequences in lung cancer." (PMID 28588743, 2017). "Our findings give insight into the properties of ZAR1 in non-oocyte tissues and its tumour suppressive role in lung cancer." (PMID 28588743, 2017). "In our present study, we further found that ZAR1 inhibited proliferation irrespective of the cancer type, as we observed ZAR1 blocked growth of three lung cancer cell lines, a cervix carcinoma and one colon cancer cell line." (PMID 28588743, 2017). "In addition, we observed the absence of ZAR1 expression in lung cancer cell lines." (PMID 28588743, 2017).
diabetes (1 paper, 2012). "Down-regulation of Zar1 transcription in diabetic mouse oocytes indicated that diabetes may affect the zygote to embryo transition." (PMID 22911868, 2012).
glioblastoma (1 paper, 2019). The most malignant astrocytic tumor (WHO grade IV). "ZAR1 mutated cancers were colorectal, endometrial, lung, glioblastoma, and mamma carcinoma (analysed using)." (PMID 31801617, 2019).
glioma (1 paper, 2017). A benign or malignant brain and spinal cord tumor that arises from glial cells (astrocytes, oligodendrocytes, ependymal cells). "It was proposed that methylation-related aberrant ZAR1 expression was unlikely to be related to glioma tumorigenesis." (PMID 28588743, 2017).
kidney cancer (1 paper, 2019). Primary or metastatic malignant neoplasm involving the kidney. "Accordingly, ZAR1 hypermethylation correlated with reduced patient survival in lung and kidney cancer." (PMID 31801617, 2019). "In summary, we report here that ZAR1 is epigenetically inactivated across cancers and has prognostic value for lung and kidney cancer as a biomarker." (PMID 31801617, 2019). "Cancer patient survival was decreased with low ZAR1 levels by the Kaplan–Meier Plot for lung and kidney cancer." (PMID 31801617, 2019). "We also show that ZAR1 methylation is a suitable biomarker for lung and kidney cancer." (PMID 31801617, 2019).
lung adenocarcinoma (1 paper, 2019). A carcinoma that arises from the lung and is characterized by the presence of malignant glandular epithelial cells. "We found that ZAR1 is expressed in the human kidney and lung and significantly hypermethylated in its CGI in lung adenocarcinoma and renal clear cell carcinoma vs. normal controls." (PMID 31801617, 2019).
ovarian carcinoma (1 paper, 2019). A malignant neoplasm originating from the surface ovarian epithelium. "In ovarian carcinoma, ZAR1 hypermethylation increases from 15% in primary tumours (n = 20) to 67% in cancer cell lines (n = 6), whereas the controls were unmethylated." (PMID 31801617, 2019).
pituitary adenomas (1 paper, 2025). "Genes and pathways examined in these studies include the ZAR1 non-promoter region, noted for frequent methylation events in pituitary adenomas." (PMID 39859246, 2025).
small cell lung carcinoma (1 paper, 2017). Small cell lung cancer (SCLC) is a highly aggressive malignant neoplasm, accounting for 10-15% of lung cancer cases, characterized byrapid growth, and early metastasis. "We then investigated ZAR1 promoter hypermethylation by COBRA in a set of non-small cell lung cancer (NSCLC) and small cell lung cancer cells (SCLC) from cell lines and primary tumour samples." (PMID 28588743, 2017).
cancer (6 papers, 2013 to 2024). A tumor composed of atypical neoplastic, often pleomorphic cells that invade other tissues. "For the first time, our study presents evidence that ZAR1, which harbours tumour suppressive properties, is a prognostic and diagnostic cancer biomarker." (PMID 31801617, 2019). "Regarding an association of human ZAR1 and cancer only, few reports exist." (PMID 28588743, 2017). "In addition, studies have shown that methylation of zar1 is associated with cancer." (PMID 38338151, 2024). "The third gene that lies in the cytoband 4p12-p11 is ZAR1, a gene known for its maternal effect and responsible for the zygote–embryo transition and indicated as tumor suppressor in cancer cell lines by inhibiting the cell cycle progression." (PMID 32784482, 2020). "We believe that in the future, also ZAR1 methylation has the potential to be part of cancer screens." (PMID 31801617, 2019). "We believe that our findings are suggesting ZAR1 reactivation in cancer as a promising target to such intervention." (PMID 31801617, 2019). "In cancer, ZAR1 is under an epigenetic control, which is a common theme for tumour suppressors in carcinogenesis." (PMID 31801617, 2019). "Across cancer cell lines, the expression of ZAR1 is significantly reduced in comparison to normal tissues (p = 2.4e-203)." (PMID 31801617, 2019). "For an in-depth view on the tumour suppressor function of ZAR1, we investigated the effects of ZAR1 reexpression in cancer." (PMID 31801617, 2019). "ZAR1 is a novel cancer biomarker for lung and kidney, which is epigenetically silenced in various cancers by DNA hypermethylation." (PMID 31801617, 2019). "In summary, ZAR1 methylation and expression reduction are putative cancer biomarkers and targets for cancer prognostics." (PMID 31801617, 2019). "We believe that our work proves that, beyond its initially reported growth-controlling role in the oocyte, ZAR1 has an exciting additional role in tissues, where it controls cellular growth and contributes to cancer suppression." (PMID 31801617, 2019). "Using epigenetic editing, we were able to modulate ZAR1 expression and methylation in cancer cell lines, further proving its epigenetic inactivation mechanism." (PMID 31801617, 2019). "In the context of cancer, evidence has been growing for a role of ZAR1, even though early reports were in part contradicting." (PMID 31801617, 2019). "ZAR1 is not only strongly hypermethylated across various cancers types but also across its complete CGI." (PMID 31801617, 2019). "We have discovered ZAR1 as a potential cancer biomarker, which should be followed by assay development and analytical validation, clinical utility validation, and ultimately clinical implementation." (PMID 31801617, 2019). "Using the CRISPR-dCas9 tools, we were able to prove that epigenetic editing and reactivation of ZAR1 is possible in cancer cell lines." (PMID 31801617, 2019). "At last, we aimed for a therapeutic and targeted epigenetic approach to reactivate the ZAR1 tumour suppressor in cancer." (PMID 31801617, 2019). "Further studies are needed to reveal through which pathways and by what partners ZAR1 inhibits cancer progression." (PMID 28588743, 2017). "All tested cancer cell lines showed endogenous reexpression of ZAR1 with 5 μM Aza and further increased expression under 10 μM Aza in a semiquantitative PCR, which was consistent when quantified for 5 μM Aza by real-time PCR." (PMID 28588743, 2017). "Exogenous expression of ZAR1 not only inhibited colony formation but also blocked cell cycle progression of cancer cell lines." (PMID 28588743, 2017). "Here, we analyzed the methylation status of ZAR1, which has been reported to be aberrantly methylated in a few human cancers." (PMID 23678400, 2013). "We did not observe frequent mutation events in ZAR1 and conclude that hypermethylation is the dominant inactivating mechanism in cancer." (PMID 31801617, 2019).